CD36 (CD36 molecule (CD36 blood group))
Diseases named in the same sentence as CD36 in open-access papers (continued):
Sharing a sentence is not in itself a finding about the gene and the disease.
tumor (continued). "CD36 is commonly upregulated to facilitate increased exogenous fatty acid uptake and has been shown to play a role in tumor cell growth, metastasis, and epithelial-mesenchymal transition in multiple cancers." (PMID 36817228, 2023). "CD36 is highly expressed in human tumor tissues and is a key receptor for lipid uptake by macrophages." (PMID 37004014, 2023). "Compared with PBMCs and non-tumor tissues, the infiltration of CD36+CD8+ T cells was higher in tumor (p < 0.0001)." (PMID 37085798, 2023). "Next, we checked the effects of the R-35 antibody on angiogenesis in endothelial-specific CD36 knockout tumors by staining the tumor tissue with pAKT and CD31 antibodies." (PMID 37100807, 2023). "A reduction in CD36 transcript levels was evident in a wide range of tumor types compared to DF tissues." (PMID 37816052, 2023). "As a critical regulator of lipid metabolism in immune cells, CD36 significantly influences their anti-tumor immune responses within the TME." (PMID 37700339, 2023). "The uptake of fatty acids by tumor-infiltrating CD8+ T cells is mediated by CD36 in the tumor microenvironment, and it enhances the accumulation of free PUFAs in tumor tissues." (PMID 37367867, 2023). "It has been demonstrated that a high-fat diet enhances the potential of CD36+ tumor cells to initiate the formation of metastases." (PMID 37063269, 2023). "To further confirm this finding, we stained fixed sections and tumor micro-array (TMA) for CD8 and CD36 by immunofluorescence in NSCLC patients, and more CD36+CD8+ T cells in tumors were found compared with non-tumor tissues (p < 0.0001)." (PMID 37085798, 2023). "CD36 is the receptor on the tumor cells that promotes lipid uptake from extracellular conditions and functions as a marker of metastasis." (PMID 36721212, 2023). "CD36 was recently identified as a marker of tumor-infiltrating PMN-MDSCs, and it plays an immunosuppressive role in mediating STAT3 signaling in MDSCs." (PMID 36788538, 2023). "Both lipid accumulation and high CD36 expression are correlated with the immunosuppressive function of TAMs and unfavorable tumor progression." (PMID 37740232, 2023). "Lipid metabolism is central to TAM differentiation and function and a tumor inhibitory effect of CD36 knockdown has been shown." (PMID 37153595, 2023). "Further mIF experiments showed that CD36+ CAFs infiltrated specifically in tumor tissues compared with adjacent liver tissues in both murine and human tissues." (PMID 36878933, 2023). "The TME promotes tumor cell proliferation by interfering with CD36-mediated lipid metabolism in immune cells." (PMID 37545500, 2023). "CD36 is expressed on tumor cells, stromal cells, and immune cells, but at different levels in different cell types and tumor stages." (PMID 37978381, 2023). "Collectively, our findings provide a comprehensive HCC transcriptomic landscape at the single-cell level and identify novel mechanisms by which CD36+ CAF-secreted MIF induced by lipid peroxidation regulates the immune evasion of tumor cells." (PMID 36878933, 2023). "In vitro tumor infiltrating lymphocytes cultures were conducted to test the effect of CD36 blockage." (PMID 37085798, 2023). "Reducing fatty acid import by neutralizing CD36 or FABP4 transporters in tumor cells controls tumor progression and metastasis, and increases sensitivity to chemotherapy." (PMID 36675280, 2023). "Studies have suggested that blocking lipid uptake via inhibition of CD36 on cytotoxic CD8+ T cells or Tregs enhances anti-tumor immune responses." (PMID 37700339, 2023). "The high expression or structural abnormalities of CD36 were closely related to tumor growth, invasion, and metastasis." (PMID 37064872, 2023). "In this experiment, the induction of Cd36 and Fabp4 transcription by rosiglitazone was significantly inhibited in both models, suggesting impairment of the Pparg pathway within the stroma of tumor-bearing mammary glands." (PMID 37816052, 2023).
tumor (continued). "Meanwhile, knocking out CD36 in Tregs of a hypoxic tumor microenvironment allowed lymphocytes to kill target cells while sustaining homeostasis, pointing to the importance of considering metabolic components like these in therapeutic treatments." (PMID 36768336, 2023). "Blocking CD36 by either pharmacologic or genetic inhibition resulted in reduced stem cell phenotypes and reduced tumor growth in vivo." (PMID 36594473, 2023). "Our results indicated that targeting inhibition or down-regulation of CD36 in LUAD cells significantly reduced tumor cell proliferation and metastasis, in which Src-Akt/Erk signaling and Rac1 activation-induced actin remodeling were involved." (PMID 37612265, 2023). "CD8+ T cells, which play a major role in anti-tumor immunity, have been confirmed to express CD36 via single cell sequencing." (PMID 37085798, 2023). "Analysis of tumor-infiltrating immune cell landscape revealed a positive correlation between CD36+CD8+ T cells and Tregs (p < 0.01) and M2-polarized macrophages (p < 0.01) but a negative correlation with Th1 (p < 0.05)." (PMID 37085798, 2023). "Our research in NSCLC showed that anti-tumor function of CD36+CD8+ T cells was impaired, with less production of GZMB and INF-γ and higher expression of PD-1 and TIGIT." (PMID 37085798, 2023). "CD36 was proved to mediate ferroptosis, and it seemed to contradict our aim of blocking CD36 to improve the anti-tumor immune response." (PMID 37085798, 2023). "Shihao Xu and coworkers have reported that CD8+ tumor-infiltrating lymphocytes (TILs) are responsive to lipids in the TME, mediated by CD36, which is associated with progressive T-cell dysfunction." (PMID 36203151, 2022). "In a recent experiment, inhibiting CD36 in intratumor Tregs by genetic ablating or using CD36 monoclonal antibodies effectively retards tumor growth and has an auxiliary effect for anti-PD-1 treatment." (PMID 36172157, 2022). "Subcutaneously injection of CD36-KO TAMs in a mouse model of lymphoma decreased tumor volume, impaired TAMs infiltration into tumor site, increased expression of M1-signature genes and decreased expression of M2-signature genes." (PMID 36686729, 2022). "Overall, our findings highlight the importance of tumor-derived lipids in educating macrophages and promoting liver metastasis via a CD36-dependent mechanism." (PMID 36184646, 2022). "CD36 impedes the function of tumor-infiltrating CD8+ T cells via the uptake of excessive fatty acids from the TME and the induction of lipid peroxidation and ferroptosis." (PMID 39872079, 2022). "We highlight the importance of lipid-enriched vesicles released by tumor cells and the upregulated expression of CD36 in macrophages in such tumor-macrophage metabolic crosstalk." (PMID 36184646, 2022). "CD36 can also participate in tumor pathogenesis by regulating the PPAR pathway and inhibiting the mitochondrial biogenesis regulator gene PPARGC1A." (PMID 36591255, 2022). "Treatment with anti-CD36 monoclonal antibodies decreased tumor burden in mouse xenografts of ovarian cancer." (PMID 35216285, 2022). "It has been demonstrated that CD36 inhibition phenocopies CD36 knockdown, decreasing tumor growth, metastatic dissemination and stemness." (PMID 36568966, 2022). "In this regard, CD36, as a key receptor for tumor metastasis, has been suggested as a therapeutic target." (PMID 35790992, 2022). "Our findings identify a role of CD36 in mediating the internalization of tumor-derived lipid-carrying vesicles by MAMs, which is beyond its general function as a fatty acid transporter." (PMID 36184646, 2022). "Our laboratory has previously shown that isogenic patient-derived xenograft (PDX) tumors, which were established from isolating tumor cells expressing high levels of CD36 (CD36high), have a higher propensity to grow subcutaneous tumors in vivo." (PMID 35008415, 2022).
tumor (continued). "In contrast, in the close interaction of MΦ with apoptotic tumor cells, we observed a CD36-dependent uptake of miR-200c into MΦ, as recently also shown for miR-375." (PMID 35336722, 2022). "TME-cholesterol-induced CD36 expression in tumor-infiltrating CD8+ T cells promotes uptake of fatty acids in tumor-infiltrating CD8+ T cells and induces lipid peroxidation and ferroptosis, eventually leading to impaired antitumor ability." (PMID 39872079, 2022). "Herein we review and discuss recent evidence supporting a key role of CD36 in the progression of different cancer types, the probable tumor progression mechanism, and its implication in the cancer stem cell (CSC) population." (PMID 36568966, 2022). "In summary, CD36 signalling requires the mitochondrial RNA modifications m5C and f5C for palmitate-induced invasion of tumour cells." (PMID 35768510, 2022). "It has been shown that the suppression of CD36 successfully inhibits the metastasis of tumor cells, whereas overexpression of CD36 reverses this inhibitory effect." (PMID 35790992, 2022). "Given the importance of CD36 in tumor progression, we foresee that this information will be available in the near future." (PMID 36568966, 2022). "Tumor cells can also increase the uptake of FAs from plasma by upregulating cell-surface receptors (e.g., cluster of differentiation 36 [CD36]) to facilitate the transport of FAs." (PMID 35790992, 2022). "In several types of cancer, there is a positive correlation between tumor CD36 expression and poor clinical outcome." (PMID 36568966, 2022). "Tumour samples from 30 patients were CD36-positive, with either a membrane or a membrane and cytoplasm pattern." (PMID 35159947, 2022). "In tumor tissue, CD36 can impair the immune surveillance of CD8+T cells by promoting the uptake of large amounts of arachidonic acid and inducing iron toxicity, lipid peroxidation, and the reduced production of cytotoxic cytokines by CD8+T cells." (PMID 36354702, 2022). "Mouse models with genetic knockout of CD36 in Tregs show reduced tumor-infiltrated Tregs and increased anti-tumor T cells." (PMID 35062950, 2022). "Phenotype of Treg-specific SREBP1 deletion is similar to that of CD36, where mice don’t develop systemic inflammatory disorder, and have improved anti-tumor responses." (PMID 36248808, 2022). "The role of CD36 in lapatinib resistance was also supported by a tumor xenograft study in mice, in which an anti-CD36 antibody markedly sensitized the resistant tumors to lapatinib." (PMID 35800378, 2022). "Tumor-treated BMDMs from Cd36−/− mice showed a distinct lipidomic profile compared with those from WT mice." (PMID 36184646, 2022). "There was a difference between patients with CD36-positive and CD36-negative tumours in the depth of tumour invasion (pT stage), with more frequent CD36-positivity in more advanced tumours (pT3b-T4) (p = 0.015)." (PMID 35159947, 2022). "In conclusion, inhibition of mitochondrial translation fully recapitulated the loss of a functional NSUN3 protein by preventing cell invasion and reducing the number of CD36-dependent metastasis-initiating tumour cells in vitro and in vivo." (PMID 35768510, 2022). "The cluster of differentiation 36 (CD36) can be involved in fatty acid intake, and increased CD36 expression can lead to tumor metastasis." (PMID 35978815, 2022). "Compared with Treg cells from other tissues and circulatory system, Treg cells in tumor have higher fatty acid absorption capacity and high expression of CD36." (PMID 35444235, 2022). "Tumor-associated immune cells play a key role in promoting tumor development in the TME and CD36 also plays an important role in regulating immunity." (PMID 36354702, 2022). "In co-culture of human PBMCs and tumor cells CD36 regulates macrophage response by enhanced lipid uptake and increased expression of pro-tumor genes in modeled TAMs (Arg1, Ccl2)." (PMID 36686729, 2022).
tumor (continued). "Treatment targeting CD36 resulted in the reduction of intratumoral Tregs and enhancement of the anti-tumor activity of tumor-infiltrating lymphocytes (TILs)." (PMID 36466873, 2022). "CD36-expressing macrophages facilitate tumor progression, pro-tumor TAM polarization and mediate fatty acid uptake from TME." (PMID 36686729, 2022). "Further CD36 has been implicated in a reduction in Treg and CD8+ T cell functionality in the tumor microenvironment, supporting tumor growth, although these findings appear to relate to CD36′s role as a lipid transporter." (PMID 36359899, 2022). "Metastatic tissue shows CD36 upregulation in comparison to primary tumor tissue, thus showing a differential role that is tissue and tumor stage dependent." (PMID 35323656, 2022). "Cd36−/− BMDMs expressed lower M2 markers (Arg1, Cd206, Il-10) but higher M1 markers (Il-12, Tnfα) compared with WT BMDMs upon incubation with tumor cells or TCM." (PMID 36184646, 2022). "The pattern of CD36 expression in tumor-infiltrating immune cell subsets correlated with the pattern of tumor-derived lipids uptake by those cells, proposing a possibility of CD36 in mediating lipid-enriched vesicles uptake." (PMID 36184646, 2022). "Those antibodies have been used as a proof-of-concept that CD36 blockage can be efficiently achieved to alter tumor progression." (PMID 36568966, 2022). "As a glycoprotein located on the cell membrane, CD36 expression in both TAMs and Tregs has been reported to promote tumor growth; hence, CD36 can be considered an important target in cancer therapy." (PMID 35454171, 2022). "CD36 has been reported to play a role in cancer and metastasis, involving tumor metabolism, immuno-editing, anti-angiogenic processes, and therapy resistance." (PMID 35892853, 2022). "In cancer, CD36 expression promotes tumor development, metastasis, drug resistance and can modulate anti-cancer immunity." (PMID 36568966, 2022). "In vivo, CD36 overexpression induces a higher tumor incidence with presence of liver metastasis, which are enriched in CD36+ cells." (PMID 36568966, 2022). "For instance, studies have demonstrated that enhanced lipid uptake and lipid oxidative phosphorylation are critical for tumor-associated macrophage polarization, and the lipid uptake-related molecule CD36 has been identified as a potential tumor marker." (PMID 36091041, 2022). "Mechanistically, CD36 participates in tumor development by favoring the lipid intake in cancer cells and promoting a switch in lipid metabolism to settle the increasing energetic demand of the tumor." (PMID 36568966, 2022). "Tumor-derived lipids uptake via CD36 subsequently triggered the orchestration of lipid metabolism in MAMs." (PMID 36184646, 2022). "First, the differential expression of CD36 was analyzed by PCR and WB in samples of metastatic tumours derived from intrasplenic injection of KM12SM and KM12L4a cells." (PMID 35957902, 2022). "In contrast to their findings, our previous study showed that CD36 does play an important role in primary CRC tumor growth, in particular when endogenously synthesized fatty acids are limited." (PMID 35008415, 2022). "In oral squamous cell carcinoma (SCC), CD36 upregulation promotes tumor metastasis, while its inhibition leads to complete remission or elimination of lymph node and lung metastases in in vivo oral carcinoma models." (PMID 36185215, 2022). "Peptides mimicking these domains block TSR protein binding to CD36 and impact tumor angiogenesis in mouse models." (PMID 35438721, 2022). "CD36 targeting primes tumors to PD-1 blockade and elicited additive anti-tumor responses with the anti-PD1 antibody therapy." (PMID 35371055, 2022). "We anticipate that the characterization of the precise effects of CD36+ stroma cells in tumor biology will be a matter of intense study in the following years." (PMID 36568966, 2022).
tumor (continued). "Activation CD36 in GBM has been related to inflammatory processes triggered by cellular debris released from the tumor site, notably induced by microglia and macrophages, key components of the tumor microenvironment." (PMID 35054787, 2022). "Tumor cells enhance the uptake of exogenous FAs, mainly through the CD36, FATP, lipid chaperone FA binding protein (FABP) and solute carrier protein family 27 (SCL27)." (PMID 36106108, 2022). "In contrast, high expression of CD36 on T cells can make T cells absorb more fatty acids from the tumor microenvironment, induce lipid peroxidation and ferroptosis, and reduce the function of T cells and the production of toxic cytokines." (PMID 36387147, 2022). "Metastatic tumor formation in the liver was largely suppressed in Cd36−/− mice compared with WT mice." (PMID 36184646, 2022). "Tumor-infiltrating CD8+ T cells accumulate large amounts of fatty acids from the TME via through CD36." (PMID 36038892, 2022). "The combination of CD36 deletion and anti-PD-1 antibody has a better anti-tumor effect than single treatment." (PMID 36387286, 2022). "CD36 molecules on the surface of tumor infiltrating CD8+ T cells can absorb oxidizing low density lipoprotein (OxLDL), activate lipid peroxidation, and inhibit the effector function of CD8+ T cells." (PMID 35444235, 2022). "CD36 is involved in long-chain FA uptake, as well as in tumour immuno-editing, metastasis, treatment response, and angiogenesis through its association with different ligands." (PMID 35159947, 2022). "As a fatty acid translocase, CD36 regulates the lipid metabolism of GC cells and its overexpression promoted the fatty acid uptake of the tumor cells." (PMID 36506554, 2022). "The genetic depletion of fatty acid translocase CD36 was previously shown to inhibit the immunomodulatory function of tumor-infiltrating MDSCs." (PMID 35664000, 2022). "In agreement, CD36 knockdown reduces tumor growth in xenotransplants, the pro-tumorigenic effect of the high in fat and cholesterol diet, and the tumor expression of stemness markers." (PMID 36568966, 2022). "Taken together, these results suggest that macrophages are endowed with a tumor-promoting phenotype after engulfing lipids from tumor cells through a CD36-dependent mechanism." (PMID 36184646, 2022). "Several studies have proposed CD36 expression as an unfavourable prognostic factor for different tumour types." (PMID 35159947, 2022). "CD36 regulates polarization of TAMs towards pro-tumor phenotype and promotes tumor growth via regulation of fatty acid (FA) metabolism." (PMID 36686729, 2022). "WT and Cd36−/− mice had comparable numbers of tumor cells reached at the livers at 1 h postinjection." (PMID 36184646, 2022). "Our data show that as we transition from normal tissue to a primary tumor and then metastasis, we see an increase in the expression of both CD36 and MMP28." (PMID 35008415, 2022). "In contrast to CD8+ TILs, tumor-infiltrating CD4 regulatory T (Treg) cells with upregulated CD36 expression persisted in the TME and suppressed the antitumor immunity." (PMID 36275711, 2022). "High CD36 expression has been correlated with poor prognosis in several tumour types, including breast, ovarian, gastric, and prostate." (PMID 35957902, 2022). "The suppressive effects of tumor-treated Cd36−/− BMDMs on CD8+ T cells were reduced when compared with WT BMDMs, as demonstrated by increased GzmB and IFNγ expression of CD8+ T cells." (PMID 36184646, 2022). "Our results suggest that tumor-derived lipids functionally reprogram macrophages through the upregulation of CD36." (PMID 36184646, 2022). "Several lines of evidence suggest that CD36, a receptor protein, is related to the onset and progression of tumours and normally acts as a cancer promoter." (PMID 36008842, 2022). "The CD36-mediated pathway is then activated to become the major source of FAs uptake, promoting tumor growth and survival." (PMID 35800378, 2022).